ERBB2 (erb-b2 receptor tyrosine kinase 2)
Diseases named in the same sentence as ERBB2 in open-access papers (continued):
Sharing a sentence is not in itself a finding about the gene and the disease.
lung cancer (continued). "For example, in ERBB2-overexpressing EGFR T790M lung cancer, we controlled and degraded ERBB2 and as well degraded EGFR, MET, and YES1 kinases that are known to drive this tumor resistance to drugs." (PMID 37359373, 2023). "Clinical trials with afatinib, pyrotinib, trastuzumab emtansine, and trastuzumab deruxtecan are being evaluated for their efficacy against EGFR‐TKI‐resistant ERBB2 amplified lung cancers." (PMID 38140788, 2023). "qRT-PCR and immunohistochemistry indicated that several key molecules such as Osteopontin/Spp1, Hmox1, Mmp12, and ERBB2 were markedly altered and/or localized in the preneoplastic lesions, suggesting their participation in the induction of lung cancer." (PMID 37513116, 2023). "Preclinical data showed that afatinib exhibits antitumor activity in ERBB2-mutant lung cancer by downregulating the phosphorylation of ERBB2 and inducing G1 arrest and apoptosis." (PMID 38067272, 2023). "Sequentially, we evaluated the targetable variations detected ability in different samples, including EGFR, ALK, BRAF V600E, KRAS, MET ex14 skipping, RET, ROS1, ERBB2, which have high evidence in lung cancer." (PMID 36167530, 2022). "For example, the ERBB2 alterations have been identified as oncogenic drivers and potential therapeutic targets in lung cancers." (PMID 35524932, 2022). "For lung cancers, lung adenocarcinomas baring mutations in EGFR, KRAS, ERBB2, and MET are reported to also host a higher number of “rearrangements”34." (PMID 35710642, 2022). "We also found lung cancer patients with ERBB2-mutant have lower TMB than non-ERBB2 mutant patients (p = 0.048)." (PMID 35911441, 2022). "Human epidermal growth factor receptor 2 (HER2, ERBB2) activating mutations occur in 2% of lung cancers." (PMID 34238332, 2021). "ERBB2 phosphorylation was markedly reduced in cells expressing L861Q plus G719X compared with lung cancer cells expressing L861Q alone." (PMID 33928034, 2021). "T-DM1 was clinically effective in ERBB2-amplified/mutant lung cancer patients, and the ORR was 51%, with a mPFS of 5 months." (PMID 33959501, 2021). "Suppressing FUT1 expression in gastric, breast and lung cancer cells reduced the expression of ErbB2, inhibited ErbB2 phosphorylation and EGF-induced ERK1/2 activation." (PMID 34069424, 2021). "In this study, we reported on the clinical and molecular characteristics of ERBB2 TMD in Asian lung cancer patients." (PMID 32478891, 2020). "Lung cancer driver genes mainly include EGFR, ERBB2, MET, RET, ALK, and ROS1, all encoding genes for receptor tyrosine kinases (RTKs)." (PMID 33537237, 2020). "Of these mutations, 97.8% (1583/1616) were found in lung cancer, with 96.71% (1530/1583) of the mutations in lung cancer were located in EGFR, 1.1% (17/1583) located in ERBB2, 0.7% (12/1583) located in BRAF, and 1.4% (23/1583) in MAP2K1." (PMID 32757330, 2020). "Lung cancer patients with ERBB2 activation have been treated using its kinase inhibitor (e.g., Lapatinib) or its mono-antibody (e.g., Trastuzumab)." (PMID 31248101, 2019). "Meanwhile, additional studies have shown that ERBB2 is a critical driver gene in human lung cancer and is frequently altered in the development of lung cancer by gene mutations and amplification." (PMID 31248101, 2019). "The details of the correlation analysis between MED24 and ERBB2 in human lung cancer are included as an example for these correlated genes." (PMID 31248101, 2019). "In vivo models have served to shed light on the investigation of the role of genes (e.g., ERBB2) in the development and progression of lung cancer." (PMID 31248101, 2019). "We not only identified that MED24 is a conserved downstream gene of ERBB2 in mouse and human lung tumors but also showed that its knockdown attenuates cell growth of lung cancer cells." (PMID 31248101, 2019).
lung cancer (continued). "Clinically, MED24 expression is associated with a poor survival rate of NSCLC patients, suggesting MED24 as a potential target for lung cancer patients, especially those with ERBB2 alterations." (PMID 31248101, 2019). "We recently showed in a large series of lung cancer patients that besides allowing the identification of EGFR, KRAS, and BRAF mutations, NGS identified a potential driver in 36% of patients (FGFR, ERBB2, AKT, MAP2K1, STK11...)." (PMID 29890761, 2018). "For example, a patient died from rapid respiratory failure and multiorgan dysfunction in a CAR-T trial targeting ErbB2 in patients suffering from lung carcinoma, due to the recognition of ErbB2 on normal lung cells." (PMID 29459866, 2018). "Somatic mutations in the kinase domain (KD) of the ERBB2 gene (primarily exon 20 insertions) were first reported in a low frequency of lung cancers and were subsequently shown to increase HER2 protein activation." (PMID 29371993, 2017). "In the clinic, the efficacy of this class of therapeutic agents has been relatively limited, with promising responses mainly observed in ERBB2+ breast and lung cancers." (PMID 27863425, 2016). "Human lung cancer HCC827 cells overexpress ErbB1 with an activating mutation in its tyrosine kinase domain and also have significant expression of ErbB2." (PMID 27286447, 2016). "We found that GLIPR1 inhibited expression of ERBB2/3 and proliferation of both lung cancer (A549, PC14) and prostate cancer (LNCaP) cells." (PMID 26988096, 2016). "Consistently with this conclusion, the RNA-Seq data demonstrated that lung cancer samples express high levels of ErbB2 and ErbB3 or FGFR3." (PMID 27480244, 2016). "For example, amplifications of EGFR in gliomas, MYCN in neuroblastoma, MYC in acute myeloid leukemia, and ERBB2 in breast, ovarian, and lung cancers have been reported." (PMID 26755558, 2016). "Recovered edges of lung cancer-specific ERBB2 and MAPK signaling pathways, with varying number of samples demonstrate the merit of SpliceNet over RNASeqNet in handling high exon to sample size ratio (smaller sample size) datasets." (PMID 25034693, 2014). "We set out to study the key effectors of resistance and sensitivity to ErbB2 tyrosine kinase inhibitors, such as lapatinib in ErbB2-positive breast and lung cancers." (PMID 25238247, 2014). "It eases the sample size bottleneck; evaluations on simulated data and lung cancer-specific ERBB2 and MAPK signaling pathways, with varying number of samples, evince the merit in handling high exon to sample size ratio datasets." (PMID 25034693, 2014). "MET amplification in lung cancer has recently been shown to be associated with activation of EGFR, ERBB2, ERBB3, and RET." (PMID 23300999, 2013). "However, none of them are approved for the treatment of patients with advanced-stage lung cancer who presented with ERBB2 amplification." (PMID 39928773, 2025). "Known lung cancer genes (EGFR, KRAS G12C, ALK, MET, RET) were found in 33 patients; 11 had genes relevant to both lung and other cancers (ERBB2, BRAF V600, NTRK), and 37 had genes typically linked to other malignancies (NF1, PIK3CA, PALB2, FGFR2B, FBX7, RAD51)." (PMID 40244261, 2025). "Specifically, the investigation revealed a connection between the phytochemical constituents and the genes CTNNB1, STAT3, HIF1A, HSP90AA1, and ERBB2, which have established links to lung cancer and play essential roles in the critical cellular pathways involved in disease progression." (PMID 39113883, 2024). "Research has found an interesting phenomenon: in lung cancer patients under 50 years old, there is a higher proportion of lung cancer with targetable genomic changes, such as EGFR mutations, ALK or ROS1 fusions, or ERBB2 insertions." (PMID 38756780, 2024).
lung cancer (continued). "In addition, there are co-mutated genes such as ATM serine/threonine kinase gene (ATM), MNNG HOS Transforming gene (MET), and erb-b2 receptor tyrosine kinase 2 gene (ERBB2), which account for more than 10% of patients with KRAS mutated lung cancer." (PMID 36675641, 2023). "It is important to note that other relevant mutations typically associated with lung cancer (such as ALK, ROS1, RET, FGFR1, ERBB2, etc.)have been found with frequencies compatible with previously published data, but without a significant difference between subgroups." (PMID 37173325, 2023). "Furthermore, in several other cancers, including lung cancer and colon cancers, HER2-targeted ADCs have proven effective in treating PDX models harboring pathogenic ERBB2 mutations." (PMID 35884581, 2022). "Mutations in lung cancer driver genes (KRAS, EGFR, BRAF, ALK, ROS1, MET, RET, and ERBB2) in the high- and low-risk groups were shown on a waterfall plot, which demonstrated that the low-risk group (20%) harbored a higher EGFR mutation frequency than did the high-risk group (8%)." (PMID 36353226, 2022). "Likewise, a study involving 7858 lung cancer patients which compared mutations between patients aged ≤45 vs >45 years observed a higher prevalence of ALK, ROS1 and RET fusions, ERBB2 exon-20 insertions and EGFR exon-19 deletions in younger patients." (PMID 36263208, 2022). "Besides, ERBB2 exon 20 insertions were found in 0.6% of the entire population and 1.9% of lung cancer patients." (PMID 35911441, 2022). "Previous studies reported that the clinical efficacy of HER2-targeted ADCs in lung cancers depends on ERBB2 mutations or amplification and not on the quantity of HER2 protein expression." (PMID 35884581, 2022). "Analysis indicated that CDKN2A, FAT1, MSH6, ARID1A, KEAP1, NF1, and SMAD4 mutation was more recurrent in patients with ERBB2 SNV/indels within the kinase domain compared with non-kinase domain in lung cancer." (PMID 35911441, 2022). "Among the detected alternations, the eight-major driver mutations of lung cancer (EGFR, ALK, ERBB2, MET, RET, ROS1, BRAF, and KRAS) could be found in 14 out of 17 (82.4%) patients using both surgical and CNB specimens." (PMID 36224661, 2022). "The frequency of ERBB2 exon 20 insertions in lung cancer patients in Brazil is scarce." (PMID 36251951, 2022). "ERBB2 S310F, S310Y, and E321G mutants exhibited poor response to Trastuzumab in lung cancer." (PMID 33377634, 2020). "Except six patients with unknown histology and one patient with mixed ADC and SCC, all patients with ERBB2 TMD mutations were ADCs at a frequency of 0.17% (38 out of 21 762), consistent with the previous report in western lung cancer patients." (PMID 32478891, 2020). "In contrast to ERBB2, most of MAP2K1 mutations found in lung cancer are β3‐αC deletions." (PMID 32757330, 2020). "Functional analysis of the top ERBB2-correlated genes (e.g., MED24) suggested that overexpression of MED24, a subunit of the Mediator complex, might be required for the ERBB2 pathway to dysregulate gene expression and the consequent lung cancer development." (PMID 31248101, 2019). "Because larger mutation screenings—including RAS, BRAF, MET (mutations, amplifications), ERBB2 (mutations, amplifications), ALK (mutations) and ROS (mutations)—were shown to be useful in the management of lung cancer patients, targeted NGS is progressively replacing single gene testing methods." (PMID 29890761, 2018). "A role of ErbB2 in tumor resistance has been also demonstrated in lung cancer." (PMID 28186982, 2017). "ERBB2 may play a role in protecting EGFR against ubiquitination, and our results suggest strong interactions between EGFR and ERBB2 in these EGFR-mutated lung cancer cells." (PMID 24189400, 2013).
lung cancer (continued). "The Keap1 mutation was only detected in patients with advanced adenocarcinoma (4.3%) and the completely exclusive status of this mutation and others, including EGFR, Kas, erbB2 and NRF2L2, is likely to improve the selection of personalized therapy for lung cancer." (PMID 24137397, 2013). "Thus, there is a strong rational for dual targeting of IGF-1R and ErbB2 or EGFR in breast or other carcinomas such as lung cancer." (PMID 24212944, 2011). "Mutations in the analogous residue of ABL1 (L273M) and ErbB2 (L755S or P) have been described in patients with imatinib-resistant chronic myelogenous leukemia (CML) and solid tumors including gastric, breast, and lung cancers, respectively." (PMID 17973572, 2007). "Though ERBB2 amplification is uncommon in melanoma, it may serve as a sensitivity marker for ADCs, enabling cross-cancer learning from targeted strategies in breast and lung cancers." (PMID 40969261, 2025). "Finally, we included 10 well-known cancer-related genes (or their hotspot-containing exons) listed as most frequently mutated in lung cancer (BRAF,EGFR,ERBB2,HRAS,KRAS,MAP2K1,MET,NF1,NRAS, and RIT1) in the panel to serve as internal controls for highly mutated regions." (PMID 40867048, 2025). "Young patients with lung cancer also tend to have a greater number of oncogenic genomic alterations, including ALK and ROS rearrangements and ERBB2 (HER2) alterations (i.e., gene amplification or mutation), suggesting that this population may benefit from targeted therapy." (PMID 38750337, 2024). "However, the frequency of ERBB2 exon 20 insertions in lung cancer patients in Brazil is scarce." (PMID 36251951, 2022). "ERBB2 exon 20 insertions may impact the clinical management of lung cancer patients." (PMID 36251951, 2022). "To examine whether the induction of EMT reduces HER2 expression, we analyzed mRNA expression of ERBB2, epithelial phenotype markers CDH1, EPCAM, MUC1 and OCLN, mesenchymal phenotype markers CDH2, FN1, SNAI2, and VIM in the A549 cell line (HER2-high human lung cancer epithelial cell line)." (PMID 34575017, 2021). "In addition to KRAS and EGFR T790 mutations, the expression of oncogenes, including MET, HER2 (ERBB2), and epidermal growth factor receptor 3 (HER3, ERBB3), is associated with drug resistance against EGFR-TKIs and leads to tumor recurrence in lung cancers." (PMID 31619200, 2019). "In addition, the ERBB2 gene is overexpressed in lung cancer and prostate cancer." (PMID 29459674, 2018). "In contrast to previous studies showing that DMTF1 LOH or null promotes tumorigenesis in Eμ-myc–induced B cell lymphoma, K-rasLA lung cancer and MMTV-neu/Erbb2 breast cancer models, we now report a growth promoting function of DMTF1 in NSC." (PMID 41481722, 2026). "In non–small cell lung cancer (NSCLC), alterations in the HER2 (ERBB2) gene define a unique molecular subtype." (PMID 40526089, 2025). "These therapies selectively target key molecular alterations in EGFR, ALK, KRAS, ROS1, MET, RET, ERBB2 (HER2), BRAF V600E, and NTRK, resulting in substantial improvements in survival rates and quality of life for lung cancer patients." (PMID 40563600, 2025). "To elucidate the expression profiles of these genes in lung cancer tissues, we visualized the expression patterns of KRAS and ERBB2, revealing high expression in tumor regions." (PMID 39830364, 2025). "We also performed GSEA analysis to further explore the mechanisms of PHF12 in lung cancer development, and the results also showed that PHF12 was related to EGFR/ErbB2 signaling pathway." (PMID 39075515, 2024). "The EGF receptor (EGFR) family consists of four transmembrane receptors, which include EGFR (HER1/erbB-1), HER2 (erbB-2/neu), HER3 (erbB-3), and HER4 (erbB-4); and is commonly overexpressed in lung cancer." (PMID 39218855, 2024). "About 10% of endometrial cancers harbored ERBB2 amplification, contrasting with 2.0% in CRC and lung cancer (p = 0.0002)." (PMID 39682116, 2024).
lung cancer (continued). "The expression levels of the top five lung cancer genes, CTNNB1, STAT3, HIF1A, HSP90AA1, and ERBB2, were determined by comparing them with the LUAD and LUSC datasets using the GEPIA2 web server." (PMID 39113883, 2024). "Expression profiling analysis in human lung tumors has confirmed the importance of the ErbB2/Akt/ELF3 signaling pathway as a prognostic biomarker and therapeutic drug target for lung cancer treatment." (PMID 37990309, 2023). "Treatment history was available in eight patients with lung cancer and target therapies against EGFR and ERBB2 were administrated." (PMID 36325957, 2023). "A set of genes involved in epithelial cell growth (ERBB2, EGF, and FGF2) and Plasminogen (PLG) were connected to Cancer and Lung cancer in the Year 2 SPP1 network." (PMID 37513116, 2023). "As we all know, Human Epidermal growth factor Receptor 2 (HER2/ERBB2) and Epidermal Growth Factor Receptor (EGFR) are two crucial biomarkers in the prognosis of lung cancer." (PMID 38137354, 2023). "hTid-1 has been found to act as an E3-ligase for several interacting proteins such as ErbB2 and EGFR that play important roles in Breast and Lung cancers respectively." (PMID 35854300, 2022). "A previous study in 36,813 Chinese lung cancer patients, focusing on eight key lung cancer driver genes (EGFR, ALK, MET, KRAS, ERBB2, ROS1, RET, and BRAF), revealed a prevalence of 0.03% for P/LP germline mutations." (PMID 35428225, 2022). "Rearrangements of MET and the ErbB family RTKs (EGFR, ERBB2, ERBB3, and ERBB4) in lung cancer are less well documented and mostly as case reports." (PMID 36369474, 2022). "A previous study in 12,833 Chinese lung cancer patients focusing on EGFR and ERBB2 has revealed a prevalence of 0.11 and 0.01% for germline mutations in the former and the latter, respectively." (PMID 33898318, 2021). "T-DM1 with osimertinib is being evaluated in EGFR mutant lung cancer (NCT03784599) and T-DM1 monotherapy is being tested in advanced ErbB2-positive colorectal cancer patients progressing after trastuzumab and lapatinib (NCT03418558)." (PMID 33081383, 2020). "The most interconnected genes were ESR1, GATA3 (DRG; breast, stomach, prostate, colorectal, lung cancer), and GREB1, all upregulated in ER+ samples, while ERBB2 which was downregulated." (PMID 32605588, 2020). "The DEGs centrally had direct interaction with EGFR, ERBB2, ERBB4, MET and TUBB, which suggested that the divergence between the primary CRC and the metastases of CRC was related to lung cancer." (PMID 30642283, 2019). "BIBW2992 inhibits ERBB2 and EGFR and targets at EGFR signaling pathway and has been widely investigated for cancers, like lung cancer and melanoma." (PMID 30972101, 2019). "Especially, the identified genes EGFR, CDKN2A, ERBB2, RB1, and CDK4 were significantly enriched for non‐small cell lung cancer, demonstrating that UniCovEx accurately identified the cancer‐related gene modules." (PMID 30828525, 2019). "In our study, we have also performed head-to-head comparison of EGFR, ERBB2, and MET gene amplifications between tissue WES and ctDNA in 48 lung cancer patients." (PMID 31739500, 2019). "Other experimental candidates include scFv, affibody and minibody (ERBB2/HER2 and FGFR1), Protein–Fc (VEGFR1 and VEGFR2) and Intact IgG (EGFR, ERBB2, and VEGF) in breast and lung cancer studies." (PMID 29455673, 2018). "Since PHLDA2 is a downstream target of EGFR/ErbB2, we analyzed PHLDA2, p-Erk and p-AKT expression in multiple lung cancer cell lines and a tissue microarray prepared with 117 well annotated primary lung cancer samples." (PMID 29861842, 2018). "Specifically, a monoclonal antibody against ErbB2, trastuzumab, and a tyrosine kinase inhibitor against EGFR, gefitinib, have improved the survival of breast and lung cancer patients." (PMID 28338617, 2017).